EPCAM (epithelial cell adhesion molecule)
Diseases named in the same sentence as EPCAM in open-access papers (continued):
Sharing a sentence is not in itself a finding about the gene and the disease.
lung carcinoma (continued). "In 25 tumor tissues from patients with early lung cancer, we confirmed the existence of CD45+EpCAM+ cells by FACS and immunofluorescent histochemical staining." (PMID 35711455, 2022). "In human lung cancer CL1 cells, EpCAM expression was severely impaired in highly invasive cells in comparison with poorly invasive ones." (PMID 36077658, 2022). "In lung cancer, common targets such as MSLN, MUC1, PSCA, and epithelial cell adhesion molecule, have intratumoral heterogeneity, leading to an unsatisfactory outcome of CAT-T cell therapy in lung cancer." (PMID 34790207, 2021). "Paclitaxel was also loaded in PEG-polylactic acid (PLA) nanoparticles that were further conjugated with the epithelial cell adhesion molecule (EpCAM, CD326), which was also overexpressed in lung cancer." (PMID 31973051, 2020). "A new platform, including EpCAM‐independent enrichment strategy, FISH, and IMSTAR HCS device, was used for the detection of CTCs in patients with lung cancer in this study." (PMID 31132233, 2019). "A panel of biomarkers (in particular, CYFRA 21-1 (cytokeratins), EPCAM (epithelial cell adhesion molecule), ProGRP (pro-gastrin-releasing peptide), CEACAM (carcinoembryonic antigen), and others are used for screening various malignancies including lung cancer." (PMID 29137182, 2017). "Expression of MTA1 and EpCAM is strongly correlated to each other in lung cancer tissues and high-level MTA1 and EpCAM predict patients’ poor prognosis in multivariate analysis." (PMID 26698569, 2015). "The results presented here proved that MTA1 upregulated EpCAM in cancers for the first time, and MTA1 overexpression promoted lung cancer invasiveness in vitro." (PMID 26698569, 2015). "We found that CD166 was highly expressed in both normal and lung cancer cells, and we used the combinations of CD166/CD44 and CD166/EpCAM for further analysis." (PMID 25881239, 2015). "Here, we report the results of a clinical study on CTCs of advanced lung cancer patients in which we compared the MCA system with the CellSearch system, which employs the conventional EpCAM-based method." (PMID 23840710, 2013). "Although EpCAM is a well-accepted marker for lung cancer, to our knowledge it has not been characterized in the context of intraoperative imaging for normal LNs in the thorax and pulmonary metastases to LNs." (PMID 41087662, 2025). "It is mainly based on immunomagnetic technologies relying on antibodies against the epithelial cell adhesion molecule (EpCAM) such as in the CellSearch system, which is the only FDA-approved technology to enrich CTCs from blood of breast, prostate, colorectal, or lung cancer patients." (PMID 36823365, 2023). "Similar to the percentage of expression observed by flow cytometric analyses, the CAF pairs were negative for both epithelial markers, CK 8,18 and EpCAM (as validated using epithelial cancer cell lines from endometrial and lung cancers, RL-95-2 and NCI-H441)." (PMID 37446260, 2023). "Consistently, minimal or no expression of EpCAM RNA and protein was detected in highly metastatic murine lung cancer cells, including LLC, MAD109, and LAP0297." (PMID 36077658, 2022). "Moreover, increased numbers of EpCAM+EGFR+ events were detected in both metastatic colorectal cancer patients and lung cancer patients compared to healthy donors." (PMID 36613466, 2022). "MM-131, a bispecific anti-EpCAM/Met antibody, exhibited both HGF-dependent and -independent inhibition of Met signaling, inhibiting the proliferation of Met-driven HCC, BC, gastric cancer and lung cancer." (PMID 36369033, 2022). "In addition, macrophage, the major cell type constituting tumor microenvironment, produces TGFβ to modulate EpCAM expression on tumor cells through TGFβ-SNAI2 axis to promote EMT and metastasis in lung cancer." (PMID 36077658, 2022). "In addition, in lung cancer cells, reports suggested that SOX2 induced EpCAM/p21/cyclin A2 by binding to the EpCAM promoter, leading to enhanced cell proliferation." (PMID 36369033, 2022).
lung carcinoma (continued). "The correlation between CD45+EpCAM+ cells, carcinoembryonic antigen (CEA), and lung cancer was investigated using receiver operating characteristic (ROC) curve analysis, which showed the sensitivity and specificity of the CD45+EpCAM+ cell to be 81.58% and 88.89%, respectively." (PMID 36147748, 2022). "Expression of WT, but not C66Y EpCAM, significantly decreased B16-F10 tumor cell invasion in vitro, and the number of lung cancer metastases following tumor challenge in vivo." (PMID 33980181, 2021). "The results showed that the combination of two BsAbs against EpCAM and MUC-1 could inhibit the growth of lung cancer more effectively in cell lines and primary tumors." (PMID 34522164, 2021). "In this regard, we used two lung cancer cell lines, i.e. H1975 and H1299, that are positive and negative for EpCAM, respectively." (PMID 34155195, 2021). "In the lung cancer single cell transcriptome dataset E-MTAB-6149, we clustered the cells by Seurat software and filtered tumor cells by the expression of EpCAM." (PMID 32854746, 2020). "In the lung cancer cell lines, the moderate EGFR expression exceeded clearly the EpCAM expression." (PMID 32504247, 2020). "Our in vitro results indicate that a CD133+/EpCAM+ population with high proliferation rate and invasive potential may have a role in progression of TNBC, as already hypothesized for HCC and lung cancer." (PMID 28870198, 2017). "In addition, patients (n = 118) with early-stage lung cancer were enrolled in this study to confirm the correlations between MTA1 and EpCAM and pathoclinical parameters by using immunohistochemistry (IHC)." (PMID 26698569, 2015). "To confirm whether EpCAM mediates the effects of MTA1 on cell invasion and migration, we conducted the transwell invasion assay and wound healing assay in lung cancer cells." (PMID 26698569, 2015). "Unlike breast or lung cancer, where EpCAM-positive, higher-shedding CTCs and abundant ctDNA repeatedly enable robust liquid-biopsy workflows, RCC presents a low-shedding, EMT-skewed phenotype with frequent EpCAM loss and lower circulating analyte abundance." (PMID 41479787, 2025). "Moreover, circulating tumour cells (CTCs) of lung cancer often display nonepithelial characteristics, and CTCs are difficult to detect through epithelial cell adhesion molecule (EpCAM)-dependent methods." (PMID 35397524, 2022). "However, no studies reported the detection of CD45+EpCAM+ cells in PBMCs of patients with lung cancer or other cancers." (PMID 36147748, 2022). "About 17% of lung cancer patients possessed high EpCAM expression levels but no gene amplification, suggesting additional mechanism(s) involved in upregulation of EpCAM expression." (PMID 36077658, 2022). "Moreover, curcumin could activate the Hippo pathway in lung cancer A549 and NCI-H1299 cells, and inhibit the expression of CD133, epithelial cell adhesion molecule (Epcam) and Octamer-binding transcription factor 4 (Oct4)." (PMID 36009200, 2022). "To examine whether the induction of EMT reduces HER2 expression, we analyzed mRNA expression of ERBB2, epithelial phenotype markers CDH1, EPCAM, MUC1 and OCLN, mesenchymal phenotype markers CDH2, FN1, SNAI2, and VIM in the A549 cell line (HER2-high human lung cancer epithelial cell line)." (PMID 34575017, 2021). "Indeed, in a comprehensive analysis that examined EMT gene expression signatures in 166 cancer cell lines and in breast and lung cancers, EpCAM expression was significantly less or absent in mesenchymal-like cancer cell lines and tumors." (PMID 34209658, 2021). "It quantified the size and EpCAM expression of over 2500 CTCs from 38 patient samples obtained from breast, prostate, lung cancers, and melanoma and found that neither CTC size nor EpCAM expression can maximize isolation efficiency as many CTCs found were small and expressed lower levels of EpCAM." (PMID 32230996, 2020).
lung carcinoma (continued). "However, gastric and lung carcinomas showed EPCAM expression, despite the lack of staining in normal gastric foveolar epithelium and lung parenchyma." (PMID 33003511, 2020). "All examined lung cancer cell lines tested GFP+/CD45− using TelomeScan F35 and could further be identified by immunohistochemical staining of epithelial (cytokeratin, E-cadherin, or EpCAM), mesenchymal (vimentin), or cancer stem cell (CD133) markers." (PMID 28432274, 2017). "In this work we showed that the microfluidic CTC capture chip could capture > 80 % of breast and lung cancer cells spiked in whole blood samples independent of the cell lines’ EpCAM expression." (PMID 27501846, 2016). "In conclusion, molecular characterization of EpCAM+ CTCs from advanced NSCLC patients provided with highly specific biomarkers with potential applicability as a “liquid biopsy” for monitoring of NSCLC patients and confirmed NOTCH1 as a potential therapeutic target to block lung cancer dissemination." (PMID 27901069, 2016). "Besides epigenetic regulation, EMT signaling, the origin of metastasis, may also contribute to EpCAM downregulation, which was supported by negative association between EMT status and EpCAM expression level in human lung cancers." (PMID 36077658, 2022). "Because our pilot experiment using plasma from lung cancer patients did not allow detection of tumour markers by WB, to compare the sensitivity of immunocapture we used plasma from patients with other epithelial tumours in which high expression of EpCAM has been reported in EVs." (PMID 35135541, 2022). "With respect to these findings, we isolated CTCs from the blood of patients with mCRPC, metastatic and non-metastatic endometrial, lung cancer, and HNSCC using comparative Hsp70 and EpCAM mAb-based bead approaches." (PMID 37626772, 2023). "Independent of EpCAM, it has been shown previously that Claudin-7 negatively regulates ERK activation and migration when expressed in a human lung carcinoma cell line." (PMID 30304739, 2018). "The non-responder sample had the lowest lymphocyte to epithelial cell ratio (T cells/EpCAM), which might explain why neither UMCD6 nor anti-PD1 induced lung cancer cell death in MOS from this patient." (PMID 38280067, 2024).
Lynch syndrome (162 papers, 2010 to 2026). "Lynch syndrome (LS) is an autosomal dominant disorder resulting from germline pathogenic variants in the DNA mismatch repair (MMR) or the EPCAM genes." (PMID 40723192, 2025). "CTE syndrome is involved in the dysfunction of the intestine caused by EpCAM malfunction, whereas Lynch syndrome is linked to the promoter hypermethylation in downstream MLH1 and MHL2 genes induced by the deletion of 3’ end of EpCAM." (PMID 38791091, 2024). "Despite having the same germline pathogenic variant (PV) in one of the mis-match repair genes or the EPCAM gene, Lynch syndrome variant heterozygotes (LSVH) exhibit a remarkable phenotypic variability in the risk of developing cancer." (PMID 38929796, 2024). "Firstly, although more than 90% of MMR-d tumors are caused by somatic mutations, germline mutations in MMR genes and EPCAM account for 5–10% of dMMR tumors, which are also known as Lynch syndrome." (PMID 36675550, 2023). "Lynch syndrome (LS) is an inherited cancer susceptibility syndrome caused by germline mutations in a DNA mismatch repair (MMR) gene or in the EPCAM gene." (PMID 37894428, 2023). "Lynch Syndrome (LS) is an inherited cancer predisposition syndrome defined by pathogenic variants in the mismatch repair (MMR) or EPCAM genes." (PMID 36344941, 2022). "No reports to date have investigated the potential role of EpCAM mutations in human cancer, although germline mutations in EpCAM impact cellular localization and are associated with congenital tufting enteropathy and Lynch syndrome." (PMID 33980181, 2021). "In conclusion, EPCAM-CL is a highly specific indicator of EPCAM germline deletion-induced Lynch syndrome-associated CRC." (PMID 26528695, 2016). "IHC for EPCAM, as well as for MMR proteins, is a simple and useful screening tool for the identification of EPCAM deletion-induced Lynch syndrome-associated CRCs and should therefore be included in standard diagnostics for Lynch syndrome." (PMID 26528695, 2016).
Lynch syndrome (continued). "The certainty diagnosis of Lynch syndrome is based on the genetic determination of the germinal line mutation of one of the MMR or EPCAM genes." (PMID 26664463, 2015). "In EPCAM deletion carriers there is a relatively low risk of endometrial cancer, which is the second most prevalent Lynch syndrome-associated malignancy in carriers of a mismatch repair mutation." (PMID 23938213, 2013). "Deletions involving the transcription termination signal of EPCAM are causative in 1% to 2.8% of families with Lynch syndrome." (PMID 23938213, 2013). "This underlines the importance of EPCAM deletions in the Lynch syndrome, as it is a more frequent cause of LS than mutations in PMS2 or MSH6." (PMID 23938213, 2013). "In conclusion, EPCAM 3’end deletions are a recurrent cause of Lynch syndrome, and detection should be implemented in routine Lynch syndrome diagnostics." (PMID 23938213, 2013). "Lynch syndrome (LS) is an autosomal-dominantly inherited cancer-predisposing disorder caused by a germline pathogenic variant (PV) in one of the mismatch repair (MMR) genes or deletions in the 3′ region of the EPCAM gene." (PMID 38929796, 2024). "It is also unclear whether LOF mutations in other regions of the EPCAM gene are responsible for the development of Lynch syndrome, including splicing disorder mutations." (PMID 38201513, 2023). "Despite recent findings that epithelial cell adhesion molecule (EPCAM) deletions can cause Lynch syndrome (LS), its clinical characteristics are still unknown." (PMID 32272879, 2020). "Diagnosis of Lynch syndrome patient could be performed by germline mutation analysis of MMR protein genes or EpCAM using DNA extracted from blood cells." (PMID 30680068, 2018). "One finding showed that a small subset of Lynch syndrome-associated CRCs carrying germline EPCAM deletions may be associated with EPCAM expression loss in tumor cells." (PMID 26528695, 2016). "Furthermore, germline deletions in EPCAM gene have been linked to Lynch syndrome." (PMID 36421850, 2022).